IL6 (interleukin 6)
Diseases named in the same sentence as IL6 in open-access papers (continued):
Sharing a sentence is not in itself a finding about the gene and the disease.
infection (continued). "Furthermore, macrophage infection assays using RAW264.7 cells revealed that isolates from clade I induced inflammatory cytokine expression (TNF-α and IL-6) at levels comparable to those observed in isolates from other clades." (PMID 39530695, 2024). "Our results demonstrate that TNF-α, IL-6, and IL-8 gene expressions, which have been reported to be overexpressed in OSCC, were increased after P. gingivalis and F. nucleatum co-culture infection, demonstrating an augmented cellular response in OKs." (PMID 38612423, 2024). "However, we found that multiple biomarkers, including IP-10, IL-6, sCD163, leptin, IL-8, and LBP, were significantly changed in the same direction across participants, either within each participant’s two pre-infection or two post-ART-suppression specimens." (PMID 38976697, 2024). "Pretreatment of UPEC-infected murine macrophage RAW264.7 cells with viable AC5 (multiplicity of infection, MOI = 1) for 24 hours enhanced macrophage-killing activity and increased proinflammatory (Nos2, Il6, and Tnfa) and anti-inflammatory (Il10) gene expression." (PMID 39091675, 2024). "Furthermore, it has been discovered that TP4 therapy decreases inflammatory cytokines at the infection site, including TNF and IL-6, and regulates epidermal healing by regulating fibroblast and keratinocyte proliferation and differentiation." (PMID 38741875, 2024). "The deletion of fliC led to decreased IL-6 secretion at 6 h post-infection but not at 3 h post-infection." (PMID 39695896, 2024). "Under pathological conditions such as stress, infection, or neurodegenerative diseases, pro-inflammatory cytokines, including tumor necrosis factor alpha (TNF-α), interleukin-1 beta (IL-1β), and interleukin-6 (IL-6), are released in excess." (PMID 39517142, 2024). "Further investigation is necessary to determine if sustained IL-6 induction and brain TRM T cells after infection could alter the neurological functions, leading to the development of long-term neurological disorders in BALB/c mice." (PMID 39475775, 2024). "Moreover, IL-6 and TNF-α enable augmentation of inflammatory cells in areas of local infection, increasing the effects of other cytokines and inflammation." (PMID 38611807, 2024). "The inflammatory cytokines TNFα, IL-4, IL-6, IL-13, IL-10, IL-12 (P40), and IL-12 (P70) along with chemokines including CCL2, CCL3, and CCL5, were significantly elevated in the plasma of c-Flip+/–mice on day 2 post-infection compared that of WT mice." (PMID 39038037, 2024). "Infection with ZIKV including MR766 induces inflammatory cytokines such as TNF-α, IL-6 and IL-1β." (PMID 39178324, 2024). "Conversely, patients with severe infection failed to mount early B and T cell responses and had persistently elevated inflammatory markers [C-reactive protein, interleukin 6 (IL-6), and tumour necrosis factor alpha (TNF-α)]." (PMID 39073768, 2024). "IIM was first described in monocytes from BCG-vaccinated patients, which showed increased expression of proinflammatory cytokines such as TNF-α, IL-6 and IFN-γ as well as increased clearance capacity in response to secondary infection with Mycobacterium tuberculosis or Candida albicans." (PMID 39720722, 2024). "It is not surprising that IL6 is significantly downregulated at 48 hours, as the strongest immune response occurred 12 hours after infection." (PMID 38441470, 2024). "In addition, PVE30 reduced the secretion of the uncontrolled downstream inflammatory cytokines IL-6 and TNF-α from host cells upon infection with HSV-1." (PMID 38185640, 2024). "Additionally, the levels of the pro-inflammatory cytokines IL-1β, IL-6, and TNF-α in serum samples collected from infected chickens at 24 h post-infection were detected." (PMID 39596124, 2024). "In contrast, the transcription levels of IL-6 (P < 0.001, ***), IL-8 (P < 0.001, ***), and TNF-α (P < 0.001, ***) were significantly lower in PAM Cl3 cells infected with vL126A/ΔNLS compared to vWT infection." (PMID 38547254, 2024).
infection (continued). "Chemokine measurement 6 hours post bacterial infection showed similar trends in some cytokines, but also highlighted the importance of cytokine kinetics within infection, as multiple chemokines were altered only at early time points, including CCL17, CCL22, IL-6, and CXCL5." (PMID 39178311, 2024). "While leukocytes, CRP, IL-6, and PCT are widely recognized as important markers of inflammation and infection, it is acknowledged that other cytokines and biomarkers may provide valuable insights into the effectiveness of hemoadsorption therapy." (PMID 39768616, 2024). "Additionally, they quantified an induction of human cytokine production at day one post-infection (including IFN-γ, IL-10, IL-1B, and IL-6)." (PMID 39061322, 2024). "Furthermore, changes in pro-inflammatory cytokines such as TNF-α and IL-6 have been shown to correlate with changes in Cytochromes P450 (CYP) expression and enzymatic activity during infection and inflammation." (PMID 37572137, 2024). "However, IL-6 and TNF-α had decreased (p < 0.01) at 12 hpi with NK-252 + infection compared to infection of S. uberis." (PMID 38397769, 2024). "After reviewing relevant literature, we found no any studies on IL-6 predicting postoperative infection in GC." (PMID 38504206, 2024). "Moreover, macrophages secrete inflammatory cytokines such as interleukin (IL) −1, IL-2, IL-6, IFN-gamma, and tumor necrosis factor alpha (TNF-α) to combat infections." (PMID 38799158, 2024). "Additionally, there was a significant increase in IL-1β, IL-6, and TNF-α levels in response to CR-hvKP57 infection, indicating varying degrees of inflammatory response." (PMID 39211794, 2024). "A transcriptome analysis of IPEC-J2 cells infected with PEDV found that the expression of IFN-α, IFN-β, TNF-α, IL-6, IL-8, and IL-12 was increased 12 h after infection, while their levels were not significantly affected during the early stage of infection." (PMID 39728983, 2024). "We observed that Ifng was significantly increased at day 1 post-infection, whereas we observed a not significant increase of Il6 at day 1 and 5 post-infection." (PMID 38404579, 2024). "Additionally, OnCL-K1 exhibits the ability to modulate the levels of inflammatory factors, such as IL-6 and IL-10, as well as chemotactic migration factors, including IL-8 and MIF, in Nile tilapia post-infection with S. agalactiae." (PMID 38473757, 2024). "Because both the non-infection and infection groups in our study had suffered surgical trauma, there was no initial difference in IL-6 in our study." (PMID 38709460, 2024). "IL-6 appeared as an early marker of neonatal sepsis, even if its levels tend to normalize during the development of infection, increasing false-negative findings." (PMID 38254697, 2024). "IL-6 production in the supernatant did not increase at 9 h post infection, whereas it increased at 24 h post infection and was lower in HuR KO cells than in WT cells." (PMID 39348382, 2024). "The review indicated that IL-6, IL-8, and PCT appear promising in predicting significant infection." (PMID 38438974, 2024). "Plasma IL-6 level at 6-h, an indicator of severe infection, was measured to confirm there were no major differences before drug/vehicle administration." (PMID 39563237, 2024). "The combination of IL-6 and PCT can function as a highly sensitive indicator for identifying severe bacterial infections in children, offering significant value in distinguishing such infections during the initial stages." (PMID 39768616, 2024). "IL-6, resistin, MIP-1α and MIP-3α were identified during a cytokine microarray of whole blood factors induced by more than 3-fold following E. coli K12, S. epidermidis 1457 or S. aureus SH1000 infection compared to control." (PMID 38672079, 2024).
infection (continued). "In addition to releasing the virus to the surrounding environment, microglia induce a robust proinflammatory response upon infection through the expression of inflammatory molecules such as IFN-α, IFN-β, TNF-α, IL-1β, IL-6, MCP-1, NO, and iNOS." (PMID 39057782, 2024). "The levels of IL-6 were found also elevated in patients with infection than in patients without infection (t = 3.5, p = 0.0007), while the levels of Neu and CRP were similar in patients with inflammation of either infectious or non-infectious etiology." (PMID 39338437, 2024). "Compared with the control group, the contents of PCT, TNF‐α, and IL‐6 were higher was lower in the DFU infection control group without significant difference (p > .05)." (PMID 38577990, 2024). "As expected, LCMV-WE infection did not induce IL-6 and the effect of TLR-2 silencing in WE-infected cells was minimal if any." (PMID 38675975, 2024). "We showed a significant increase in NET release to Pseudomonas aeruginosa PAO1 when challenged with inflammatory mediators tumor necrosis factor-α [20 ng mL−1] and interleukin-6 [50 ng mL−1], but not leukotriene B4 [20 nM], compared to the infection alone." (PMID 38189525, 2024). "Lastly, other pro-inflammatory cytokines, such as TNF-α, IL-6, IL-8, and IL-9, exhibited significant upregulation at 1dpi compared to controls, and with no further induction at later time points post infection." (PMID 38459109, 2024). "IL6 and TNF were significantly upregulated in VRI_stage1 and VRI_stage2, contributing to the inflammatory response, and it was observed that they were upregulated in both basal and secretory cells at 28 dpi, which is a considerable time after infection." (PMID 39735182, 2024). "Therefore, we examined the expression of cytokine genes (IL-1β, IL-6, IL-10, TNF-α, and GM-CSF) after infection." (PMID 38903792, 2024). "Secondary outcomes involved the evaluation of mean daily gastric residual volume, mechanical ventilation period, infection rates within the ICU, length of hospitalization, mortality rates, nutritional status and inflammatory markers, specifically serum albumin and interleukin-6 levels." (PMID 38906990, 2024). "Furthermore, the study examined the levels of IL-6, IL-10, IL-8, and MIF gene expression in different tissues and organs following artificial infection of tilapia, as well as the extent of tissue damage." (PMID 38473757, 2024). "infection in the gallbladder triggers an intense inflammatory response, manifested by elevated levels (more than 10-fold) of proinflammatory mediators such as tumor necrosis factor-α (TNF-α), interleukin-6 (IL-6) and monocyte chemotactic protein-1 (MCP1)." (PMID 38774627, 2024). "Moreover, CRS, fever, PCT, IL-6, and CRP emerged as potential indicators for the early detection of infections." (PMID 38956649, 2024). "Therefore, we quantified TNF-α, IL-1β, and IL-6 cytokine levels in PAM culture supernatants that were collected at 24- and 48-h post-infection using commercially available ELISA kits." (PMID 38664855, 2024). "In our study, the absence of clinical signs of infection during the neonates’ maternity ward stay precludes the influence of prenatal and perinatal infections on leukocyte and IL-6 values." (PMID 39062232, 2024). "The lower concentration of IL-6 and IL-8 induced by the attenuated PDCoV HNZK-02-P150 infection may also have contributed to the less lesions in piglets." (PMID 38349151, 2024). "Caspase-3, caspase-8, or pan-caspase inhibition did not alter secretion of IFN-α2, IFN-γ, MCP-1, IL-6, IL-10, IL-12p70 or IL-23, as elevated levels of these cytokines were detected in all infection conditions." (PMID 38408992, 2024). "For example, during early infection of P. falciparum, the infected RBC-derived PFHRPII interacted with BMECs, activating endothelial NFκB signaling, leading to the release of inflammatory mediators such as IL-6 IL-1B CCL5 and IFNβ1." (PMID 38360663, 2024).
infection (continued). "Additionally, a study indicated that following infection with RABV, there was an upregulation in cytokine expression (IL-1α, IL-1β, IL-6 and IL-10), concurrently accompanied by the recruitment of inflammatory cells into the CNS to facilitate viral clearance." (PMID 39273091, 2024). "Conversely, SmLE infection resulted in elevated levels of IL-2, IL-4, IL-5 and IL-6 and a decrease in IL-13 in C57BL/6 but not in BALB/c mice." (PMID 38711063, 2024). "Noteworthy, next to IL-6 and CXCL10, we also investigated whether NSPHs could be triggered to release IFN-α2 and IFN-β upon infection with VZVeGFP-ORF23 or SeVeGFP, as a sign of intrinsic anti-viral response." (PMID 39351233, 2024). "SAG suppressed ERK1/2 phosphorylation, IL-6, MIP-2, and E-selectin upregulation upon infection." (PMID 38360663, 2024). "IL-6 and C-reactive protein (CRP) levels serve as indicators of stress during delivery, yet discerning the specific stressor, be it premature birth, prenatal maternal infections, or intrapartum infections, remains challenging." (PMID 39062232, 2024). "IL-6 is not a specific marker for infection, as its levels can increase in response to tissue injury or inflammatory stimuli." (PMID 39135875, 2024). "Upon infection and mediated by PKC-ζ, SPHK2 is phosphorylated, increasing its nuclear localization and thereby upregulating S1P and increasing histone acetylation and IL-6 and TNFα secretion." (PMID 38474268, 2024). "Macrophages, derived from monocytes, are pivotal in engulfing pathogens and dead cells through phagocytosis while also releasing pro-inflammatory cytokines like interleukin-1 (IL-1), IL-6, and tumor necrosis factor-alpha (TNF-α) to recruit additional immune cells to sites of infection." (PMID 39518533, 2024). "Concurrently, the infection of TOCs with IBV DMV/1639 resulted in a pronounced increase in IL1-β mRNA expression at 3, 6, and 12 hpi (P < 0.05) and IL-6 mRNA expression at 3 and 6 hpi (P < 0.05) compared with both IBV DMV/1639-infected TOCs and non-infected controls." (PMID 39472003, 2024). "Consistent with this, it has been shown previously that the presence of AA enhanced the release of IL-6 and CXCL-8 (IL-8) during RV16 infection of a human respiratory epithelial cell line (Beas-2B);45 however, changes in the lipid membrane profile as well as viral replication were not analyzed." (PMID 38179897, 2024). "While C. burnetii infection of mouse macrophages is immunologically silent at early times post-infection and does not induce type I IFNs, by late times post-infection, we observed IFNβ and IL-6 responses in a STING-dependent manner." (PMID 38459007, 2024). "Regarding clinical samples, there were significant differences in the levels of 3 cytokines, including IL-6, IL-12p70, and G-CSF, between the infection groups (S aureus and K pneumonia group) and the negative control group." (PMID 39969364, 2024). "Matching the data collected during the physical characterization of the NTHi-NHNE infection, expression levels of key chemo- and cytokines (e.g. CXCL8, IL-6, IL-1β, CCL3, CXCL1 & CXCL2) and genes involved in ECM remodelling and inflammation (PLAU, Serpine1, MMP9) increased further on day14." (PMID 38990812, 2024). "Using small molecule inhibitors designed to inhibit Mip, we demonstrated that treatment of B. pseudomallei-infected murine macrophages with the inhibitor AN_CH_37 resulted in a decrease in secreted pro-inflammatory cytokines IL-1β, TNFα and IL-6, and an increase in MCP-1, 24 hours post-infection." (PMID 38590438, 2024). "Elevated levels of the cytokines IL-1β (32.23±12.58 pg/ml) and IL-6 (45.12±16.03 pg/ml) were detected in the cerebrospinal fluid of these patients without any signs of infection." (PMID 39006838, 2024). "Specifically, TNFα, IL-1β, IL-6, IL-10, and type I interferons (IFN-β) decreased early during infection in all three regimes of mice immunization with rVSV-HTNV-GP." (PMID 38341504, 2024).
infection (continued). "However, CLEC2.Fc efficiently inhibited the expression of proinflammatory cytokines (IL‐6, TNF‐α, IFN‐γ, and IL‐10) and chemokines (CXCL1, CXCL2, CXCL5, CCL2, IP‐10) at day 3 and day 5 post‐infection (blue columns)." (PMID 37211986, 2023). "Despite these limitations, the present study was able to show that symptomatic P. falciparum infection is associated with increased levels of the cytokines IL-10, IL-13, IL-6, IFN-γ and IL-12p70 while asymptomatic infection is marked by increased levels of IL-10, IL-13, IL-22 and IL-12p70." (PMID 36787308, 2023). "A further indication is provided by the fact that infection with the CagA negative strain (clinical isolate #6) induced IL6 expression in GES-1 cells independently of NF-κB activation." (PMID 37894827, 2023). "When RSV associated with PM10 comes into contact with respiratory epithelial cells, there is a greater increase in the secretion of inflammatory mediators (IL-6 and IL-8) compared to infection without PM1028." (PMID 37803025, 2023). "We observed a NS1 dosage-dependent host response for genes involved in the inflammatory response (IL-6, IFNB1) and interferon stimulation (IFIT1, MX1, ISG15), with the IAV-NS1-T infection generating an intermediate phenotype at both the transcript and at the protein levels." (PMID 37876781, 2023). "Although this infection is abortive in monocyte-derived macrophages (MDM) and dendritic cells (MDDC), it can induce the production of a wide repertoire of pro-inflammatory cytokines, such as IL-6 or TNF-α." (PMID 37175995, 2023). "In contrast to the neutralization of IFN-γ and TNF or IL-1β, neutralizing IL-6 activity in the post-acute phase of infection did not improve the pathology or fibrotic sequelae post infection." (PMID 38077031, 2023). "As the first line of defense of the lung, the airway epithelium provides a physical barrier to prevent infection but also produces chemokines and cytokines such as TNF-α, IL-1β, IL-6, IL-8, and IL-12 that are important mediators in both lung defense and inflammation." (PMID 38102682, 2023). "Elevated expression of multiple inflammatory genes, including IL6, TNF, IL10, and IL1B, were observed in the CD163+MRC1+TREM2 Mac and CD163+MRC1− subsets in both Cohort 1 and 2 after infection." (PMID 37024448, 2023). "Here, high levels of cytokines and chemokines (TNF-α, IFN-γ, IP-10, IL-1β, and IL-6), with significantly upregulated TNF-α levels 24 h after infection could be detected." (PMID 37163429, 2023). "IL-6 has been repeatedly described as predictive of TCMR, but also is a strong marker of infection." (PMID 36670678, 2023). "Notably, our results showed an upregulated transcriptional expression of cytokines (IL-1β, IL-6 and TNF-α), adhesion molecules (VCAM-1, ICAM-1) and chemokines (CXCL1 and CXCL2) after infection in both brain cortex and hippocampus." (PMID 36778380, 2023). "IL-6, CSF 3, CXCL1, and IL-17 levels were significantly higher during infection." (PMID 37790429, 2023). "Infection with virulent ASFV isolates often results in exacerbated immune responses, with increased levels of serum pro-inflammatory interleukins (IL-1α, IL-1β, IL-6), TNF and chemokines (CCL2, CCL5, CXCL10)." (PMID 36680273, 2023). "Indeed, the importance of IL-6 in the overall phagoptotic phenomenon was corroborated by stimulating microglia with heat-killed B. abortus (HKBA), a surrogate of infection." (PMID 38322014, 2023). "Baseline (medium-treated) BAL cells from obese individuals had significantly reduced spontaneous and post-infection production of IL-6, CXCL8/IL-8 and TNF compared to non-obese individuals." (PMID 37857661, 2023). "Furthermore, there is an interesting indication from animal studies that andrographolide can reduce inflammation (measured by IL-6 and TNF-α), whilst keeping sufficient inflammatory activity to fight off an infection." (PMID 37765014, 2023). "The 2308ΔeryA infection induced similar levels of IL-6 and TNF-α to 2308 infection." (PMID 37671873, 2023).